CASP1 (caspase 1)
Diseases named in the same sentence as CASP1 in open-access papers (continued):
Sharing a sentence is not in itself a finding about the gene and the disease.
infection (continued). "In rodents, the activation of caspase-1 provoked the release of IL-18 which, in turn, induced IFN-γ to prime caspase-11 activity, whereas caspase-4 transgenic mice did not necessitate IFN-γ priming upstream of caspase-4 to control the infection." (PMID 33329561, 2020). "On the contrary, infection of THP-1 cells with L. infantum in the absence or presence of nigericin did not increase the percentage of cells expressing active caspase-1 in comparison to control non-infected/non-stimulated cells." (PMID 31961876, 2020). "To confirm the roles of Caspase-1/11 and Gsdmd in the pathogenicity of SS2-induced STSS in vivo, we infected IP WT, Caspase-1/11−/−, and Gsdmd−/− mice with a higher dose of 2 × 109 CFU SS2 and observed their activity and survival every 2 h until 24 h post infection." (PMID 32922370, 2020). "Notably, the cleaved forms of both Caspase 3 and Caspase 1, markers of inflammasome activation, were clearly detected by the inhibition of small EV secretion in THP-1 cells following infection with BCG." (PMID 32466233, 2020). "These apparently contradictory findings are probably best reconciled by assuming that NLRP7 serves as a negative regulator of inflammation in quiescent cells, while in response to a proper stimulus, such as infection, NLRP7 promotes inflammasome assembly and caspase-1 activation." (PMID 32550001, 2020). "Under the infection of Salmonella, NLRC4 and NLRP3 inflammasomes could be activated within 1 h, cut the pro-caspase-1 into active caspase-1 in macrophages and induce pyroptosis." (PMID 33324360, 2020). "So among NLRC4−/− group, the expression of Caspase-1 was absent with either PA infection or ASC intervention." (PMID 33489931, 2020). "Another similarity between caspase-1 and TLR2 KO mice was the loss of bone flaps at later intervals, where 18% and 38% of caspase-1 KO animals had no bone flaps at days 21 or 28 post-infection, respectively." (PMID 32290861, 2020). "Later in the same year, it was reported by the Cui group that ZIKV can target cGAS for degradation via the enhanced stabilization of caspase-1 by nonstructural protein NS1 during infection." (PMID 32899347, 2020). "Interestingly, at day 7 post-infection (time of resolution), the spleen size was augmented in all RIPK3–/–, Casp-1/11–/–, and Casp-1/11–/–/RIPK3–/– DKO mice in comparison to WT." (PMID 32328060, 2020). "This is substantiated by the finding that neither TLR2 nor caspase-1 KO mice displayed overt signs of morbidity and survived the infection similar to WT animals." (PMID 32290861, 2020). "Recent studies revealed caspase-8 upregulation during infections in the absence of either caspase-1 or GsdmD21." (PMID 31209224, 2019). "Moreover, infection of human monocytic cell line with P. gingivalis activates NLRP3 and AIM2 inflammasome through caspase 1 activation, which produces the processing of pro-IL-1β to its active form IL-1β." (PMID 31049022, 2019). "Infection experiments with Il18−/− mice and the administration of recombinant IL-18 to caspase-1−/− mice showed that IL-18 was not important for resistance to the intestinal phase of infection, but rather to the systemic infection." (PMID 30717382, 2019). "Caspase-1 inactivates IL-33, and therefore, IL-33 is not produced when cells are activated to form an inflammasome by infection with bacteria harboring TLR ligands." (PMID 30717382, 2019). "Similarly, infection of human corneal epithelial cells with virulent HSV-1 clinical isolate KOS79 induced a significant early activation of Caspase-1, IL-1β and IL-18." (PMID 31367214, 2019). "We observed no reduction in the frequency or absolute cell numbers of peritoneal CD4+IFN-γ+ T cells in the absence of NLRP3, ASC, or Casp1/11 by day 8 post-infection." (PMID 31194844, 2019). "Next, MNV infections in primary macrophages lacking both caspase-1 and -11, or lacking the adaptor protein ASC demonstrated that MNV induced maturation and secretion of IL-1β in an ASC- and caspase-1-dependent manner." (PMID 31017981, 2019).
infection (continued). "Recent studies have also demonstrated that caspase-8 is upregulated during infection-induced inflammasome activation in the absence of either caspase-1 or GsdmD21." (PMID 31209224, 2019). "However, infection with Salmonella typhimurium, activator of the NLRC4 inflammasome, led to caspase-1 activation and increased IL-1β production in BMDMs from Lgal3−/− mice." (PMID 31406212, 2019). "Infection performed in macrophages derived from Nlrp3–/–, Aim2–/–, Asc–/–and Casp1/11–/–mice indicate that the NLRP3, but not AIM2 inflammasome is essential for production of inflammatory cytokines, such as IL-1β." (PMID 31479495, 2019). "As expected, KCl, but not NaCl treatment inhibited IL-1β and Casp1 p20 production in response to infection, confirming the participation of the NLRP3 inflammasome in human cells." (PMID 31754185, 2019). "We confirmed by flow cytometry that the caspase-1 inhibitor did not affect the infection efficiency or cell viability compared to the vehicle control." (PMID 29440572, 2018). "Consistent with previous reports, infection with MCMV for 40 hours induced IL-18 in the serum and led to MCMV-specific IFNγ production by splenic NK cells in wild-type controls, whereas these responses were dampened in Casp1/11−/− mice." (PMID 29855523, 2018). "In this study, caspase-1/11 KO mice had reduced pulmonary levels of KC (CXCL1, an important neutrophil chemoattractant), and also exhibited a significantly lower number of neutrophils in BALF after infection." (PMID 30456207, 2018). "This pathway effectively accounts for resistance to infection in macrophages and in vivo when caspase-1 is absent." (PMID 28771586, 2017). "The anti-infection defense of recombinant L. monocytogenes that enhanced the inflammasome activation is due to caspase-1-induced pyroptosis, but not due to the secretion of IL-1β and IL-18." (PMID 28468643, 2017). "Alternatively, it is possible that the response to infection with MK mutants leads to changes in signaling or cellular redox balance that inactivate either the AIM2 receptor or downstream signaling components, including caspase-1 itself." (PMID 28325762, 2017). "Infections in macrophages from littermate control mice indicated that caspase-8 activation occur in Casp1/11-/-, but not in Casp1/11+/- and Casp1/11+/+ macrophages." (PMID 28771586, 2017). "We therefore investigated whether Syk signaling was required for NLRP3 inflammasome-dependent caspase-1 activation and IL-1β production following SEA infection." (PMID 28808303, 2017). "Conversely, forced expression of Asc strongly increased larval resistance to the infection and caspase-1 activity, both effects being largely independent of Caiap." (PMID 29123523, 2017). "Caspase-1 and -11 were not required for efficient replication or macrophage killing at higher infection rates, suggesting that besides pyroptosis L. pneumophila can utilize other mechanisms to induce macrophage death during egress." (PMID 28261564, 2017). "In contrast, pore formation was evident in Casp1/11-/- but not in Asc/Casp1/11-/- macrophages in response to fliI- infection." (PMID 28771586, 2017). "Conversely, forced expression of Asc strongly increased larval resistance to the infection and caspase-1 activity, these effects being largely independent of Gbp4." (PMID 27363812, 2016). "In the present study, after finding that neutrophils make a significant contribution to IL-1β production during infection, we observed that live GBS induce in these cells activation of endosomal TLRs and of the caspase-1 inflammasome, leading to the release of mature IL-1β." (PMID 27509078, 2016). "To determine whether NLRP3, ASC and Caspase-1 are activated in peripheral blood monocytes following infection by H. parasuis, we evaluated the expression of NLRP3, ASC and caspase-1 at mRNA levels by qRT-PCR." (PMID 27502767, 2016).
infection (continued). "After human infection it efficiently replicates in alveolar macrophages without activating inflammasome assembly and cleavage of caspase-1." (PMID 27148204, 2016). "After Ft LVS infection IL-1β and IL-18 levels are similar between Aim2- and Nlrp3-deficient mice, yet mice deficient in Aim2, ASC, or caspase-1/11 do not reproduce the survival phenotype of Nlrp3 mice." (PMID 27926940, 2016). "On the contrary, ΔYopM/YopM rescue strain infection triggered increased HMGB1 release without inducing caspase-1 cleavage and IL-1β secretion." (PMID 27929533, 2016). "Unlike Nlrp3-deficient mice, Aim2-/-, Caspase-1/11-/-, Asc-/-, and IL-1R-/- mice died within 8–11 dpi after lethal Ft LVS infection or between 6 and 7 dpi after SchuS4." (PMID 27926940, 2016). "In addition, reduced caspase 1 and IL1-β levels were noted in cells and tissue infected with strains having a colonizing phenotype, while both were strongly induced following infection with the cytotoxic strains." (PMID 27511873, 2016). "Our data show that MOI 0.1 is efficient to induce early IL-1β and caspase-1 activation and that cytokine and chemokine kinetics induced by MOI 1 versus MOI 0.1 is different suggesting that intracellular pathways are regulated by infection dosages." (PMID 27833923, 2016). "We found increased caspase-1 expression in PPE32-incubated or MS_PPE32-infected macrophages in comparison with control group, and the cleaved caspase-9 and caspase-3 were enhanced after MS_PPE32 infection." (PMID 27634911, 2016). "After 18 hours of infection the difference in caspase-1 activity in control and UCH-L5 overexpressing cells was not as significant, most likely because many cells were already not viable and only the end-point of the process was measured." (PMID 26267804, 2015). "In the absence of caspase-1, the F/G actin ratio slightly decreased throughout the elapsed infection time." (PMID 26686473, 2015). "We found that the infection of wild-type C57BL/6 BMDMs (BL/6 BMDMs) with C. burnetii does not induce the cleavage of caspase-1 p20 subunit." (PMID 26687278, 2015). "Caspase-1 was activated and cleaved in brain homogenates at 24 h after infection in S. pneumoniae D39- or TIGR4-challenged mice, unlike in PBS-treated control mice." (PMID 26683708, 2015). "Herein, we report that C. burnetii fails to induce caspase-1 activation upon the infection of primary mouse macrophages." (PMID 26687278, 2015). "Using FACS we determined that infection with S. marcescens did not lead to the activation of caspase-1 or caspases-3/7, further ruling out pyroptosis and apoptosis as the responsible form of cell death." (PMID 26659062, 2015). "For example, mice lacking caspase-1 displayed higher bacterial numbers in organs following infection with F. novicida." (PMID 24600590, 2014). "We examined caspase-1 activity in mock- and HIV-1SF162-infected microglia at 24 hr post-infection, which revealed minimal caspase-1 activity (green) in mock-infected cells (Hoescht counterstained nuclei) but HIV-infected microglia exhibited abundant caspase-1 activity." (PMID 24886384, 2014). "Regarding the release of IL-1β from microglia in response to HIV-1 or FIV infections and its relationship to pathogenesis, the multivariate analyses of FIV-infected animals suggested that elevated expression of caspase-1, NLRP3 and IL-1β contributed to the development of brain disease." (PMID 24886384, 2014). "Contrary to expectations, the cleavage of precursor IL-1β to its mature form did not require caspase-1 during primary infections within the lung despite being required by bone marrow-derived macrophages exposed to live bacteria." (PMID 25198773, 2014). "While NLRC4 appeared to be the main upstream candidate for caspase-1 activation, NLRC4-deficient mice showed only minor or no defects in bacterial control during infections." (PMID 24381573, 2013).
infection (continued). "Cillóniz and coworkers demonstrated robust transcriptional changes of inflammatory response genes, including upregulation of inflammasome genes (e.g., CASP1, IL1B, and NLRP3), in response to H5N1 VN1203 compared to 1918 pandemic influenza virus at day 1 post-infection." (PMID 23895213, 2013). "Secretion of both cytokines is significantly diminished during infection with L. pneumophila lacking DotA, an essential component of the T4SS (ΔdotA Lp), and is significantly diminished in caspase-1/caspase-11-deficient (Casp1−/−Casp11−/−) macrophages as well." (PMID 23762026, 2013). "Western blots of lysates from infected macrophages revealed that neither 1,25D nor infection altered expression of caspase-1 in its pro-form." (PMID 23762029, 2013). "Macrophages infected with mutants lacking sdhA gene trigger Aim2-dependent activation of caspase-1, secretion of IL-1β and pyroptosis, which is reversible by infection with genetically complemented bacteria." (PMID 24324933, 2013). "Under low MOI infection conditions where there is minimal induction of pyroptosis, it was revealed that the induction of autophagy dampens pyroptosis in response to L. pneumophila, and turnover of autophagosomes requires NAIP5, NLRC4, and caspase-1." (PMID 24409420, 2013). "Our results indicate that Salmonella evasion of caspase-1 dependent flagellin recognition is critical for establishing infection and that evasion of TLR5 and caspase-1 dependent flagellin recognition helps Salmonella induce intestinal inflammation and establish a niche in the inflamed gut." (PMID 23977202, 2013). "Macrophages isolated from the NLRP3−/− and caspase-1−/− mice failed to kill amastigotes and exhibited an infection index that was even higher than that observed in MyD88−/− macrophages." (PMID 24098823, 2013). "Recently, secretion of IL-1α independent of caspase-1 and caspase-11 has also been shown to participate in neutrophil recruitment and infection control." (PMID 24324933, 2013). "Our findings do not rule out the possibility that caspase-1 activation is important for protection of mice against subcutaneous infection with a hypercytotoxic Y. pestis." (PMID 22563435, 2012). "Cleavage of caspase-7 during L. monocytogenes infection did not require caspase-1 or key adaptors of the primary pathways of innate immune signaling in this infection, ASC, RIP2 and MyD88." (PMID 22807671, 2012). "Caspase-7 cleavage occurred in the absence of caspase-1, distinct from the activation cascade observed during infection by S. Typhimurium and L. pneumophila." (PMID 22807671, 2012). "NLRC4 regulates Caspase-1 activation and IL-1β processing in response to infection with various gram-negative bacteria." (PMID 22701621, 2012). "Previously, Gao and Abu-Kwaik demonstrated that activation of caspase-3, but not caspase-1, is essential for apoptosis induced upon infection by L. pneumophila, but the initial events of caspase induction remained unclear at that time." (PMID 21470397, 2011). "At 6 h post-infection, we detected the processed p20 subunit of caspase-1 in lysates from infected wild-type, but not TLR2−/− macrophages." (PMID 21698237, 2011). "Measurement of the bacterial burdens in lungs, spleens, and livers of infected mice 24 hours (data not shown) and 48 hours post-infection revealed that Nlrc4-/- and Casp1-/- mice carried considerably higher burdens in all three organs than WT mice." (PMID 22241982, 2011). "This is in contrast to macrophages from ASC−/− and caspase-1−/− mice, which did not undergo cell death between 6 and 14 h post-infection (data not shown), in agreement with previous studies." (PMID 21698237, 2011). "By infection of Staphylococcus aureus, NALP3, which is a member of the NLR family, forms the inflammasome with caspase-1, ASC and Cardinal and leads to the activation of caspase-1." (PMID 20735596, 2009).
infection (continued). "We further demonstrate that inhibition of the inflammasome with a caspase-1 inhibitor did not prevent the induction of NF-κB regulated cytokines following infection with vMyxM013-KO virus, but did block the activation of IL-1β." (PMID 19851467, 2009). "Despite this, L. pneumophila replicated to a similar extent in macrophages lacking caspase-1 or caspase-7, suggesting that for L. pneumophila to establish infection, it is particularly important to delay apoptosis during the early stages of infection." (PMID 19343209, 2009). "tularensis infection results in extensive host-cell death through a caspase-3 dependent mechanism and not caspase-1." (PMID 19936232, 2009). "Here, we demonstrate that vMyxM013-KO infection of THP-1 cells also induces other cytokines and chemokines (TNF, IL-6, and MCP-1) that are regulated by the NF-κB pathway, in addition to the cytokines controlled by the caspase 1/inflammasome complex." (PMID 19851467, 2009). "Oral infection with S. Typhimurium of caspase-1–deficient mice, but not ASC−/−, NALP3−/−, or IPAF−/− animals, leads to increased susceptibility to infection." (PMID 18166077, 2007). "Additionally, we observed that ΔnleB/espL triggered enhanced macrophage cytotoxicity, caspase-8 and caspase-1 processing, GSDMD cleavage and IL-1β maturation compared to ΔnleB infection in LPS-primed macrophages, while ΔnleB/espL complemented with nleB or espL caused less cell lysis (Fig. EV5A)." (PMID 40128366, 2025). "Infection with MHV-68 resulted in an elevated abundance of cytokines (TNF-α and IL-6) that triggered inflammation, an upsurge in pyroptosis-related molecules involving caspase-1, IL-1β, and IL-18, along with a decrease in IL-10 concentration, an anti-inflammatory cytokine, in peritoneal macrophages." (PMID 40041420, 2025). "Additionally, the infection also resulted in the absence of active caspase-1 p20 in LPS/Aβ-stimulated pMG, and a marked reduction in caspase-1 activation in LPS/Nig-stimulated cells." (PMID 41162989, 2025). "Notably, even in the absence of infection, blocking caspase-1 (CASP1), the effector molecule of the NLRP3 inflammasome, drastically lowers NETosis in human neutrophils." (PMID 40433617, 2025). "Similarly, in a model of primary HLH induced in perforin-deficient mice by infection with lymphocytic or mouse choriomeningitis virus, the genetic removal of ASC or caspase-1 failed to prevent HLH lethality despite a large reduction in IL-18 levels." (PMID 40632844, 2025). "Notably, the intensity of GSDME, GSDMD, caspase-3, and caspase-1 cleavage was strikingly more pronounced over the time course of Brazil/78 infection, correlating with significantly greater IL-1β and LDH release at 18 and 24 h post-infection." (PMID 40481027, 2025). "However, we found no benefit for Casp1-/- mice after infection with an equal dose of E. coli, whereas a mild benefit was observed when they were infected with twice the dose of E. coli." (PMID 40359428, 2025). "Recent studies have demonstrated that infection with G. parasuis serotype 5 triggers an inflammatory response by activating the NLRP3 inflammasome and induces pyroptosis through the cleavage of gasdermin D (GSDMD) and the activation of Caspase-1, thereby amplifying the inflammatory cascade." (PMID 40665414, 2025). "Therefore, we assessed the activation of caspase-1 in lung macrophages and found that it was strongly active after infection with A. baumannii in healthy but not post-CLP mice." (PMID 40202049, 2025). "To study the redundancies between these pathways, we also treated Casp1-/-, Mlkl-/- or Zbp1-/- mice with an anti-dsRNA antibody before E. coli pneumonia and found that dsRNA neutralization did not reduce neutrophil death in these mice after infection." (PMID 40359428, 2025).